DLAT (dihydrolipoamide S-acetyltransferase)
Diseases named in the same sentence as DLAT in open-access papers (continued):
Sharing a sentence is not in itself a finding about the gene and the disease.
cancer (continued). "DLAT can catalyze the conversion of pyruvate into Acetyl CoA, promote oxidative phosphorylation, ATP generation and catabolic reactions, which are important in the development of cancer." (PMID 36685880, 2022). "Germline mutations in LIAS, LIPT2 and LIPT1 result in impaired PDHc and OGDHc activity, but ABHD11 loss did not significantly alter DLAT lipoylation in several cancer lines." (PMID 32792488, 2020). "However, the relevance and function of DLAT in cancers such as HCC, are unclear." (PMID 38799437, 2024). "However, whether DLAT, as a key molecule mediating cuproptosis, can bring new breakthroughs for cancer therapy deserves more attention." (PMID 36975441, 2023). "Thus, DLAT was intuitively supposed to be downregulated in cancer if the Warburg effect is assumed." (PMID 35869499, 2022). "In this pan-cancer analysis, we systematically profiled the expression and prognostic value of eight well-characterized cuproptosis-related genes—FDX1, LIAS, LIPT1, DLD, DLAT, PDHA1, PDHB, and SLC31A1—across 34 cancer types." (PMID 40601654, 2025). "In Cuproptosis-related genes, SPC25 was positively correlated with GCSH, CDKN2A, PDHB, PDHA1, DLAT, DLD, and SLC31A1 of pan-cancer." (PMID 38605119, 2024). "Among these cancers, the cuproptosis key genes, LIAS, FDX1, and DLAT tended to show copy number deletion, while DLD tended to show copy number amplification." (PMID 38573998, 2024). "To further explore the role of the gene set (DLAT, IDH3B, and MAP3K4) across diverse cancer types, we analyzed their expression levels and mutant profiles." (PMID 36835825, 2023). "The results showed that cuproptosis-related genes such as PDHB, PDHA1, DLAT, DLD, LIPT1 were significantly positively correlated with FDX1 in pan-cancer." (PMID 35991547, 2022). "The expression of DLAT, LIAS, and ATP7B was negatively correlated with the methylation in most of the cancer types." (PMID 36276096, 2022). "The transcriptional levels of DLAT, FDX1, DBT, DLD, PDHB, and GCSH negatively correlate with methylation in part of tumors (> 7 cancer types)." (PMID 36209249, 2022). "We found that the expression of PDHA1, GLS, DLAT, PDHB and MTF1 were differed between cancer and paracancer." (PMID 36620594, 2022). "The mitochondrial version also shows increased conversion of pyruvate to acetyl-CoA in cancer cells through upregulation of PDHB and DLAT." (PMID 36282866, 2022). "In the stemness analysis, STAD was the most striking cancer type, which was positively correlated with the expression of ATP7B, SLC31A1, FDX1, and DLAT." (PMID 36276096, 2022). "Indeed, downregulation of several glycolysis genes deeply involved in cancer progression (ENO1, ME1, SLC2A4RG, PFKL and DLAT) was confirmed by RT-qPCR in siRNF40-treated HCC1806 cells." (PMID 37770435, 2023). "Notably, there was a robust relationship between the expression of DLAT and major histocompatibility complex (MHC) genes in all cancer types, particularly in KIRC, LIHC, PRAD, TGCT, and UVM." (PMID 37199628, 2023). "With the molecular mechanisms and biological functions of DLAT in tumorigenesis not yet fully revealed, our team initiated the pan-cancer analysis to find a solution." (PMID 36949759, 2023). "Intriguingly, DLAT exhibited a positive correlation with M1 macrophages in COADREAD, KIPAN, KIRC, and READ, partially explaining its protective function for overall survival in these cancer types." (PMID 37199628, 2023). "On the contrary, KIRCs were found to potentially have a lower copper cell death in cancer tissue because their anti-cuproptosis gene ATP7B was upregulated with pro-copper metabolism-related cell death genes SLC31A1, FDX1, DLAT, and LIAS downregulated in cancer tissues." (PMID 36276096, 2022).
cancer (continued). "DLAT is the initiator of the TCA cycle, and overexpressed DLAT promotes glycolysis and inhibits the breakdown of pyruvate into acetyl-CoA instead of promoting the TCA cycle, thereby aggravating the malignant development of NSCLC; PDHA1 plays a role in HCC cancer metastasis and clinical pathology." (PMID 38078880, 2023). "Interestingly, in our study, correlation analysis revealed a negative correlation between immune cell infiltration and the expression levels of DLAT and DBT, suggesting that cuproptosis-related genes such as DLAT and DBT may promote the invasion of cancer cells through immunosuppression." (PMID 38722401, 2024). "However, the roles and mechanisms of DLAT in various cancers have not yet been fully revealed." (PMID 36949759, 2023). "Finally, the data on the gene expression profiles of cancer cell lines were integrated in the Genomics of Drug Sensitivity in Cancer (GDSC) database for drug sensitivity to fully explore the potential value of CDKN2A, DLAT, DLST, GLS, and PDHA1 genes as novel therapeutic targets." (PMID 36891150, 2023). "For example, the expression of DLAT, LIAS, and ATP7B was negatively correlated with the methylation in most of the cancer types, while the expression of SLC31A and FDX1 was not remarkably correlated with the methylation in most of the cancer types." (PMID 36276096, 2022). "Results showed that the cancer–noncancer protein expression patterns of ATP7B, SLC31A1, DLAT, and LIAS were mostly consistent with the patterns at the mRNA level but that of FDX1 was not." (PMID 36276096, 2022).
infection (11 papers, 2008 to 2025). The state of being infected such as from the introduction of a foreign agent such as serum, vaccine, antigenic substance or organism. "The authors confirmed a vital role of dlaT in establishing infection and searched for dlaT inhibitors trough screening a library of chemicals." (PMID 33603720, 2020). "Mitochondrial proteins are among these dually modified proteins, in agreement with our finding of infection-enhanced acetylations on TCA cycle proteins, including PDHB, DLAT, and DLD, at sites known as ubiquitinated." (PMID 30470744, 2018). "Three DlaT peptides were cloned in the L. monocytogenes strain, and the infection of mice with this strain induced similar immunomodulatory effects as those observed in mice receiving P. freudenreichii P.UF1, thus confirming the immunomodulatory role of DlaT." (PMID 40563526, 2025).
digestive diseases (1 paper, 2022). "The four overlapping genes, including LIAS, DLAT, DBT, and PDHA1, were dysregulated expressed in the interaction between the four digestive diseases using the Venn diagram." (PMID 36405733, 2022).
heart disease (1 paper, 2022). "DLAT (also known as E2; PBC; PDCE2; PDC-E2) is also a gene that is highly expressed in heart tissue but has not been paid attention to in heart disease research." (PMID 35886059, 2022).
neurodevelopmental disorder (1 paper, 2025). A behavioral and cognitive disorder with onset during the developmental period that involves impaired or aberrant development of intellectual, motor, or social functions. "rs10891314 is located in the DLAT gene, which is associated with a rare neurodevelopmental disorder, pyruvate dehydrogenase E2 deficiency." (PMID 39572686, 2025).
DLAT also shares sentences with these, for which no sentence is quoted: liver autoimmune diseases (5 papers); lung squamous cell carcinoma (5); stomach adenocarcinoma (5); gastrointestinal tumors (4); Autoimmunity (3); Bacterial infections (3); cholangiocarcinoma (3); diabetes (3); ovarian serous cystadenocarcinoma (3); prostate adenocarcinoma (3); bladder urothelial carcinoma (2); cervical squamous cell carcinoma (2); cholangitis (2); Cirrhosis (2); degenerative disease (2); endocervical adenocarcinoma (2); germ cell tumor (2); kidney cancer (2); liver (2); liver fibrosis (2); lymphoid neoplasm (2); triple-negative breast carcinoma (2); urinary tract infection (2); uterine corpus endometrial carcinoma (2); abscess (1); acute kidney injury (1); adrenal cancer (1); alcoholic liver diseases (1); Alexander disease (1); bacteremia (1).
A further 45 diseases each share a sentence with DLAT in 1 paper.